MMP2 (matrix metallopeptidase 2)
Diseases named in the same sentence as MMP2 in open-access papers (continued):
Sharing a sentence is not in itself a finding about the gene and the disease.
tumor (continued). "Treatment of AsPC-1 xenografted mice with embelin induced the expression of E-cadherin and inhibited the expression of MMP-2, MMP-9, Snail, Slug, and Zeb-1 in tumor tissues compared to untreated control group." (PMID 24694877, 2014). "In tumor cells, EMMPRIN promotes the production of MMP-1, MMP-2, and MMP-9 and facilitates the synthesis of MT1-MMP and MT2-MMP." (PMID 24705283, 2014). "Function: Like MMP-2, MMP-9 derived from both tumor cells and tumor microenvironment plays important roles in the process of cancer metastasis." (PMID 24978435, 2014). "Embelin inhibited the production of pro-angiogenic IL-8 and VEGF/VEGFR as well as invasiveness-promoting MMP-2 and MMP-9 thus blocking production of tumorigenic mediators in the microenvironment of the tumor." (PMID 24694877, 2014). "MMP-2 and MMP-9 immunoexpression in tumor cells was cytoplasmic, finely granular, and varied in intensity and percentage." (PMID 25097794, 2014). "These vesicles were shown to contain bioactive matrix metalloproteinases (MMP2 and MMP9), enzymes that have critical importance in tumour invasion, in addition to RNA, ADP-ribosylation factor 6 and caveolin-1." (PMID 24931391, 2014). "Recent studies have also demonstrated that adenovirus-mediated transfer of siRNA against MMP-2 results in impaired expression of VEGF and tumor-induced angiogenesis both in vitro and in vivo." (PMID 25233229, 2014). "CD147, designated as extracellular MMP inducer (EMMPRIN), is overexpressed in tumor cells and is capable of stimulating the production of various MMPs such as MMP-1, MMP-2, MMP-3, MMP-9, and MMP-11." (PMID 24996644, 2014). "The CCR1+ myeloid cells appeared to enhance tumor invasion by producing metalloproteinases MMP9 and MMP2." (PMID 25326065, 2014). "As for matrix metallopeptidase-2 (MMP-2) and metallopeptidase-9 (MMP-9), they contribute greatly to tumor metastasis and invasion and are considered to be predictive markers for cancer." (PMID 25250322, 2014). "MAP2K4 overexpression increases the expression of heat shock protein 27 (HSP27) protein and protease production, with the largest effect upon matrix metalloproteinase 2 (MMP-2), both in vitro and in mouse tumor samples." (PMID 25019290, 2014). "Genetic ablation of CCR2 markedly attenuates tumor formation with reduced HSC accumulation and MMP-2 expression." (PMID 24966464, 2014). "Follistatin was significantly upregulated in tumor stroma, as compared to tumor cells (p < 0.001) while G-CSF, HGF and MMP-2 showed a trend for an increased expression in the stromal compartment." (PMID 25483099, 2014). "There was a significant correlation between MMP-2 immunoreactivity in inflammatory cells and the presence of distant metastases and between TIMP-2 expression in inflammatory cells and tumor size, nodal involvement, and distant metastases." (PMID 24395652, 2014). "Among all of the tumor samples that were analyzed, tumors from the TE-1LM-ATF4 and TE-1HM-SCR cell groups showed strong and moderate MMP-2 and MMP-7 staining." (PMID 25078779, 2014). "It was proven that matrix metalloproteinase MMP2 and MMP9 degraded the basement membrane was a crucial step that promote tumor invasion and metastasis in many types of tumors." (PMID 24876827, 2014). "Equally, the tumor suppressor, PDCD4 is directly targeted by miR-21 in HCC and as a result, the downstream molecular signalling cascade including MMP-2, MMP-9 and phospho c-jun were all shown to be affected." (PMID 24670365, 2014). "M2 TAMs support tumor progression through the release of immunosuppressive (i.e., CCL2 and IL-10), proangiogenic (i.e., IL-8 and VEGF), and tissue remodeling (i.e., MMP-2 and MMP-9) factors." (PMID 25136593, 2014). "This functioned as a tumor environment-sensitive water-soluble PTX prodrug and an MMP2-sensitive building block for a PTX nanopreparation." (PMID 24795633, 2014).
tumor (continued). "Our previous study demonstrated that CD147 in tumor cells modulates fibroblasts, as well as HCC cells themselves to produce MMP-2 and MMP-9, promoting HCC invasion and metastasis." (PMID 24996644, 2014). "Recent studies have found that it has anticancer activity with its mechanism of action to inhibit the activity of MMP-2 and MMP-9 and thereby to inhibit the tumor growth, invasion, metastasis, and angiogenesis in cancer tissues." (PMID 24971318, 2014). "MMPs, especially MMP-2 and MMP-9, as well as their endogenous inhibitors (TIMPs, especially TIMP1) are known to be important in tumor development, tumor cell invasion and metastasis." (PMID 24959847, 2014). "MMP-2 and MMP-9 metalloproteinases, our research subjects, have been reported as essential in the tumor dissemination and progression process by many authors." (PMID 24737953, 2014). "It has been proposed that STC2 facilitates tumor cell migration through epithelial-mesenchymal transition (EMT) and upregulation of MMP-2 and MMP-9 in hypoxic conditions." (PMID 24606961, 2014). "DTCs were detected using immunocytochemistry, the level of tumor hypoxia using NMR spectroscopy, CD68, CD34, VEGF, and VEGFR-1 (Flt-1) expression using immunohistochemistry, and MMP-2 and MMP-9 activity using zymography." (PMID 24669218, 2014). "Staining of NB cell lines and NB-TIC xenograft tissues revealed the co- or juxtalocalization of TLX and MMP-2 and CD15, in particular at the edges of TLX-expressing tumor clusters, suggesting them to be migratory cells." (PMID 25356871, 2014). "In MMP-2-positive, SCC-7 tumor-bearing mice, the administered probes demonstrated preferential tumor accumulation with a strong fluorescence signal." (PMID 25988156, 2014). "The expression levels of MMP2 and HIF-1α mRNA and its protein were significantly high when the tumor had a diameter >5 cm, was intrahepatic, exhibited portal metastasis and was of TNM stage III or IV." (PMID 25013467, 2014). "In the present study we demonstrate that dietary AXT inhibits tumour progression based on abrogation of the JAK/STAT3 pathway and its downstream targets cyclin D1, MMP-2, -9, and VEGF in the HBP carcinogenesis model." (PMID 25296162, 2014). "Leptin promotes tumor growth, eliciting the activity of several signaling pathways such as insulin-like growth factor-1 (IGF-1) and HER2 and inducing the expression of MMP-2, MMP-9, and VEGF, which finally promote cell migration and metastatic spreading." (PMID 25136593, 2014). "TAMs and MDSCs contributed to tumor angiogenesis by producing a wide variety of angiogenic factors such as VEGF, TGF-β, CXCL8, platelet-derived growth factor (PDGF), and MMPs such as MMP-2 and MMP-9." (PMID 24966464, 2014). "We therefore measured the effects of embelin on the expression of E-cadherin, Snail, Slug, ZEB1, MMP-2 and MMP-9 in tumor tissues." (PMID 24694877, 2014). "Taken together, these results suggest that MMP-2 and MMP-7 are involved in and essential for ATF4-mediated tumor invasion and metastasis." (PMID 25078779, 2014). "MMP-2 and MMP-9, the most extensively studied MMPs in tumor invasion, mainly degrade collagen IV and a number of other ECM proteins." (PMID 25026293, 2014). "In particular, MMP-2 and MMP-9 are collagenases and are crucial for tumor invasion and metastasis by degrading collagen IV." (PMID 23877152, 2013). "For example genistein inhibited cell invasion reducing expression of MMP2 and MMP9 in human prostate epithelial and metastatic cells where tumor progression is positively correlated with the expression of MMP." (PMID 23554959, 2013). "SNAI2 has a positive effect on α3β1-mediated invasiveness of tumor cells, since SNAI2 promotes the production of MMP-2 and MMP-9." (PMID 24260309, 2013). "As MMP2 and 9, substrates in the plasmin proteolytic cascade, are involved in the degradation of ECM and invasion of tumor cells, the effect of blocking ENO1 on the activation and activity of MMP2/9 was next examined." (PMID 23894455, 2013).
tumor (continued). "Collectively, our data implicate astrocyte-derived MMP-2 and MMP-9 as critical players that facilitate tumor cell migration and invasion leading to brain metastasis." (PMID 24324647, 2013). "Taken together, these in vitro results suggest that astrocyte secreted MMP-2 and MMP-9 proteins partially mediate tumor cell invasion." (PMID 24324647, 2013). "Proof of concept for this prodrug approach has been generated for the tumor stroma marker FAP with urokinase plasminogen activator (uPa) and matrix metalloproteinase-2 (MMP2) mediated cleavage of the TNFR1 domain." (PMID 23840967, 2013). "MMP2 and MMP9 are important mediators for tumor progression and metastasis, and in our experiments we observed the levels of pro- and active-MMP2, MMP9 were the lowest in the combination therapy group among three groups." (PMID 24304581, 2013). "Given that MMP2, MMP9, vimentin, and ZEB1 were regarded as potential elemental genes implying the pro-metastatic state and higher malignancy of tumor cells, as well as E2F1 downstream target genes, RT-PCR was performed to detect changes in mRNA levels." (PMID 24023875, 2013). "Matrix metalloproteinase-2 (MMP-2) and IL-6 participate in endothelial cell injury and the extravasation of tumor cells, and IL-1β, IL-6, and TGF-β are involved in tumor progression." (PMID 23710200, 2013). "MMP-2 and MMP-9 are critical enzymes for ECM degradation, which is a critical step in tumor metastasis." (PMID 23877152, 2013). "Among various MMP types, MMP-2 and MMP-9 play pivotal roles in tumor cell invasion and metastasis by degradation of type IV collagen, a major component of the ECM." (PMID 24085323, 2013). "We have shown that MMP-2 can directly modulate innate and adaptive immune responses toward melanoma by not only being recognized by specific CD4+ and CD8+ tumor-infiltrating T cells, but also by modulating DC function to polarize TH2 responses." (PMID 24339825, 2013). "The cytokine TNF-α promotes tumor proliferation by inducing the release of matrix metalloproteinase (MMP), particularly the gelatinases MMP-2 and MMP-9, which promote tumor growth and metastasis." (PMID 23977085, 2013). "In particular, the activities of MMP-2 and MMP-9 are often found to be elevated in tumor tissues and malignant cancer cells." (PMID 24223164, 2013). "majorana significantly reduced the expression of several NFκB downstream target genes (MMP-2, MMP-9, uPAR, ICAM-1 and VEGF) involved in tumor metastasis." (PMID 23874773, 2013). "Recently, more reports have shown that miR-29 family regulated tumorigenesis and tumor progression by targeting DNMT3A, DNMT3B, TIAM1, cyclin E, MMP2, ID1, SPARC and COL3A1." (PMID 23936390, 2013). "Of these overexpressed genes, 5 (CXCR4, CXCL12, MMP2, MMP9 and MMP13) were selected on the basis of their strong correlation with tumor metastasis and were validated by qPCR." (PMID 24179538, 2013). "The gelatinases, MMP-2 (gelatinase A) and MMP-9 (gelatinase B), are two members of the MMP family and play a critical role in tumor invasion and metastasis." (PMID 23935727, 2013). "Several studies have demonstrated that MMP-2 and MMP-9 are critical for tumor invasion and metastasis by degrading collagen IV, a main component of basement membranes." (PMID 23877152, 2013). "Our study, for the first time, demonstrated that PER1 and MMP-2 expression, MI of BSCC cells and tumor weight had significant differences among 4 time groups." (PMID 23405233, 2013). "An imbalance between the proteolytic activity of MMP2 and TIMP2 is responsible for degradation of extracellular matrix (ECM) components, and plays a crucial role in tumor invasion and in metastasis formation." (PMID 24083576, 2013). "In the present study, we found that GLY not only attenuated enzyme activities and protein expression level of MMP-2 and MMP-9 in cell lysate, respectively, but also reduced MMP-2 and MMP-9 protein expression in tumor lysate (Supplemental S1)." (PMID 23573143, 2013).
tumor (continued). "Although TIMP-3 and 4 have a high affinity for MMP-2, the proteins effectively inhibit MT1-MMP, thereby activating the MMP-2 zymogen process and inhibiting tumor cell growth and metastasis." (PMID 23819566, 2013). "MMP-2 and MT1-MMP facilitate tumor invasion, as both are able to degrade extracellular matrix (ECM) as well as non-ECM substrates." (PMID 23967226, 2013). "The inactive precursor of TGF-β can be processed by MMP-2, and TGF-β induces gene transcprition of MMP-2, thus generating a vicious circle leading to further tumor growth." (PMID 24023566, 2013). "In particular, colon metastases are known to induce MMP2 and MMP9 expression in stromal cells, and MMP inhibitors reduce tumor growth and metastasis in animal models." (PMID 24023955, 2013). "The PHGDH shRNA dramatically reduced the expression levels of MMP-2 and VEGF, which are oncogenes important for tumor invasion and angiogenesis." (PMID 23229761, 2013). "MMP-2 expression was observed in both large and small tumor cells, while MMP-9 expression was observed primarily in large tumor cells." (PMID 23536878, 2013). "Matrix metalloproteinases, especially MMP-2 and MMP-9, are also key regulators of tumor cell invasion and metastasis due to their ability to degrade type IV collagen, a major component of the ECM." (PMID 23900236, 2013). "Proof of concept in vitro as well as in vivo for such tumor selective activation was reported for the stromal marker FAP and the proteases uPA and MMP2." (PMID 23840967, 2013). "MMP2 and MMP9 are activated by CREB and appear to play important roles in tumor invasion and metastasis." (PMID 24113161, 2013). "To further explore the mechanism of EFEMP1 on tumor invasion and migration, we assayed culture supernatants from HEC-1B, RL95-2 and transfected cells for the concentration of MMP-2 and MMP-9." (PMID 23840707, 2013). "With optimal cut-off levels, MMP-2 and VEGF had sensitivities of 82.1 and 95.2% and specificities of 95.7 and 89.5%, respectively, in differentiating tumor patients from controls." (PMID 24400253, 2013). "Since MMP-2 and MMP-9 showed more tumor cell invasive activities than MMP-3, we focused on MMP-2 and -9 moving forward." (PMID 24324647, 2013). "The 5 randomly selected gene expression changes observed using the Human Tumor Metastasis RT2 Profiler PCR array (CXCR4, CXCL12, MMP2, MMP9 and MMP13) were confirmed using qPCR." (PMID 24179538, 2013). "The protein levels of Cyclin D1, Pro-Caspase-3, Bcl-2, MMP2 and MMP9 in tumor extracts were examined by western blot." (PMID 23874680, 2013). "Gelatinases (MMP2 and MMP9), two important isoforms in the MMP family, are considered to be closely correlated with tumor invasion and metastasis." (PMID 23226772, 2012). "AD cells had high expression of MMP2 and MMP9, proteases involved with matrix remodeling during tumor dissemination." (PMID 23056490, 2012). "We therefore examined the effect of sLRP6E1E2 on expression of MMP-2 and MMP-9, which play a critical role in angiogenesis, tumor growth, and metastasis." (PMID 22606268, 2012). "Its antiangiogenic properties include inhibition of MMP-2 and MMP-9 secretion from tumor cells and inhibition of endothelial cell proliferation and migration." (PMID 21977033, 2012). "Thus stromal cell MMP-2 expression maybe a consequence of tumor cell activity." (PMID 23227342, 2012). "Proteins like matrix metalloproteinase 2 (MMP2), MMP9 and serine protease urokinase-type plasminogen activator (uPA) which play an important role in tumour invasion and metastasis, are under the transcription control of NFκB." (PMID 23905066, 2012). "Membrane-associated MT1-MMP mediates proteolysis and activates the precursor of MMP-2 (pro-MMP-2), which localizes on the cell surface, and these events occur at the invasive edge of tumor cell nests." (PMID 23304519, 2012). "A number of factors, such as MMP-2 and vascular endothelial growth factor (VEGF), are involved in tumor growth, invasion, and metastasis." (PMID 23013480, 2012).
tumor (continued). "Considering stimulation, membrane type-1 MMP (MT1-MMP), also known as MMP14 is one of main activators, and also Interleukin-8 (IL-8) upregulates MMP2 and MMP9 in tumor cells, which is thought to be responsible for its angiogenic activity." (PMID 22695075, 2012). "We also examined the expression of MMP2 and MMP9, which are known to play a role in tumour invasiveness, LVI and induce angiogenesis in several types of cancer." (PMID 23304558, 2012). "Expression of MMP-9 has been reported in breast, colon, and lung cancers, as well as skin tumors, and the expression of both MMP-2 and MMP-9 has been correlated with local invasion of the tumor, lymph node metastasis, and survival rates." (PMID 22159401, 2012). "We noticed that VEGFA, HIF1A, SOX4, SOX9, MMP2, TGFB1 genes are overexpressed together with S6K1 in all 4 tumour types investigated." (PMID 22570651, 2012). "Matrix metalloproteinase 2 (MMP2) was proposed as a potential therapeutic target, based on its high-level expression in many human tumours and its ability to degrade type IV collagen." (PMID 22863329, 2012). "MMP-2 (gelatinase A) and MMP-9 (gelatinase B) play important roles in destroying the basement membrane of tumor vessels, and their expression correlates with metastasis." (PMID 22159401, 2012). "Morphometric analysis of the tumor cells revealed the differences in the rate of cell spreading after MMP-2 inhibition, indicating that MMP-2 activity affected the spreading of tumor cells." (PMID 22848537, 2012). "Matrix metalloproteinases, especially MMP-2 and MMP-9 play pivotal roles in tumor cell invasion and metastasis due to their ability to degrade type IV collagen, a major component of the ECM." (PMID 22736175, 2012). "Conversely, MMP-2 is secreted in an inactive state and therefore, proteinases that can activate MMP-2 are indirectly capable of regulating TGFβ bioavailability and tumor survival." (PMID 22238668, 2012). "Earlier studies have shown that downregulation of MMP-2 with adenovirus mediated delivery of MMP-2 (ad-MMP-2) siRNA reduced invasion, migration and angiogenesis in A549 cells in vitro and inhibited tumor growth and metastasis in vivo." (PMID 22962598, 2012). "Among the many MMPs, MMP-2 and MMP-9 are reported to be closely related to the tumor metastasis in ESCC." (PMID 22433565, 2012). "In OS, sorafenib inhibits proliferation of tumour growth, angiogenesis (VEGF), invasion (MMP2), and the emergence of pulmonary metastases (Erzin/β4-intégrin/PI3K) and induces apoptosis." (PMID 23226965, 2012). "MMP-2, MMP-9, and MMP-14 have been reported to be involved in tumor angiogenesis and extracellular matrix remodeling." (PMID 22496834, 2012). "Second, the cells expressed higher level of COX Va also had higher expressions and activities of MMP-2 and MMP-9, which had been reported to be related to migration and invasion in different types of tumor cells." (PMID 22748147, 2012). "To begin to elucidate mechanisms mediating the improved efficacy of the combinedtherapy group, we assessed the expression of several proteins involved ininvasiveness and angiogenesis (MMP-2, XIAP, OPN, and VEGF) in the tumor tissueof the treated groups." (PMID 22569271, 2012). "VEGF, MMP-2 and MMP-9 are thought to be critically involved in the processes of tumor cell migration, invasion and metastasis." (PMID 22640183, 2012). "A stoichiometric balance was required to facilitate tumor cell migration and invasion, where MT1-MMP activated MMP-2 and the αvβ3 integrin promoted its maturation and release." (PMID 23201642, 2012). "MMP-2 directly binds to αvβ3 integrin, which is a regulator of MMP-2 activation during tumor cell migration." (PMID 22848537, 2012). "Since osteoblasts express MMP-2 in the tumor-bone microenvironment and given our data suggesting host derived MMP-2 was impacting tumor survival in vivo, we next tested the impact of wild type and MMP-2 null primary osteoblasts on tumor survival in vitro." (PMID 22238668, 2012).